TRIP10 (thyroid hormone receptor interactor 10)
Description:
Required for translocation of GLUT4 to the plasma membrane in response to insulin signaling (By similarity). Required to coordinate membrane tubulation with reorganization of the actin cytoskeleton during endocytosis. Binds to lipids such as phosphatidylinositol 4,5-bisphosphate and phosphatidylserine and promotes membrane invagination and the formation of tubules. Also promotes CDC42-induced actin polymerization by recruiting WASL/N-WASP which in turn activates the Arp2/3 complex. Actin polymerization may promote the fission of membrane tubules to form endocytic vesicles. Required for the formation of podosomes, actin-rich adhesion structures specific to monocyte-derived cells. May be required for the lysosomal retention of FASLG/FASL.
Synonyms: hSTP; TRIP-10; CIP4; STOT; STP
Tractability: Antibody: UniProt places it where antibodies can reach, with medium confidence; its Gene Ontology location is reachable by antibodies, with medium confidence. PROTAC: ubiquitination databases record sites on it; its protein half-life has been measured.
Gene: Protein-coding gene on chromosome 19 (6,737,925 to 6,751,530, forward strand). Ensembl gene ENSG00000125733.
Subcellular location: Cytoplasm, cytoskeleton; Cytoplasm, cell cortex; Lysosome; Golgi apparatus; Cell membrane; Cell projection, phagocytic cup; Cytoplasm, perinuclear region (Isoform 5)
Subcellular location (Human Protein Atlas): Vesicles; Nucleoplasm
Pathways (Reactome):
Signal Transduction: RHOQ GTPase cycle
Vesicle-mediated transport: Clathrin-mediated endocytosis
Gene Ontology:
Molecular function: identical protein binding; protein binding
Biological process: actin cytoskeleton organization; cell communication; signal transduction
Cellular component: extracellular exosome; cytoplasm; cytosol; cell cortex; cytoskeleton; Golgi apparatus; lysosome; perinuclear region of cytoplasm; phagocytic cup; plasma membrane
Genetic constraint (gnomAD): Loss-of-function variants: 52 observed, 80.51 expected, observed/expected ratio (o/e) 0.65, 90% interval 0.52 to 0.81. The upper end of that interval is the gene's LOEUF score, 0.81, which puts it in group 3 of 6, group 1 being the genes least tolerant of losing a copy. Missense variants: 741 observed, 826.5 expected, observed/expected ratio (o/e) 0.9, 90% interval 0.84 to 0.95. Synonymous variants: 307 observed, 311.8 expected, observed/expected ratio (o/e) 0.98, 90% interval 0.9 to 1.08.
Homologues: Orthologues: chimpanzee TRIP10 (99% identical), macaque TRIP10 (98% identical), dog TRIP10 (96% identical), pig TRIP10 (95% identical), rat Trip10 (92% identical), mouse Trip10 (91% identical), guinea pig TRIP10 (86% identical), zebrafish trip10a (55% identical), zebrafish trip10b (36% identical), Drosophila melanogaster Cip4 (34% identical), Caenorhabditis elegans toca-1 (24% identical), Caenorhabditis elegans toca-2 (21% identical). Paralogues in human: FNBP1L (53% identical), FNBP1 (52% identical).
Diseases named in the same sentence as TRIP10 in open-access papers:
TRIP10 is named in the same sentence as 43 diseases in open-access papers, as found by Europe PMC text mining. Sharing a sentence is not in itself a finding about the gene and the disease. The quoted sentences say what the papers report.
breast carcinoma (10 papers, 2011 to 2023). "In particular, in breast cancer, it has been also confirmed that TRIP10 expression can be regulated by epigenetic mechanisms such as DNA methylation." (PMID 30786922, 2019). "Similar methylation patterns were observed in tumor specimens, Trip10 was hypermethylated in breast cancer but hypomethylated in liver cancer compared to adjacent non-tumor tissues." (PMID 21299869, 2011). "Taken together, our results show that Trip10 expression in brain tumors, breast cancer, liver cancer, and ovarian cancer is regulated by DNA methylation, but the methylation level varies among these cancer types." (PMID 21299869, 2011). "We previously found that Trip10 is highly expressed in estrogen receptor-expressing (ER+) breast cancer cells." (PMID 21299869, 2011). "Together, these data demonstrate that Trip10 is subject to epigenetic modification by DNA methylation in breast cancer and liver cancer tumorigenesis." (PMID 21299869, 2011). "Because ER- breast cancer is generally more malignant than ER+ breast cancer, these data suggest that Trip10 hypermethylation promotes tumorigenesis." (PMID 21299869, 2011). "We found that Trip10 is hypermethylated in brain tumor and breast cancer, but hypomethylated in liver cancer." (PMID 21299869, 2011). "In MCF7 cells, an estrogen receptor-positive (ER+) breast cancer cell line, Trip10 is strongly expressed." (PMID 21299869, 2011). "To test this hypothesis and evaluate whether Trip10 is epigenetically regulated by DNA methylation in other cancers, we evaluated DNA methylation of Trip10 in liver cancer, brain tumor, ovarian cancer, and breast cancer." (PMID 21299869, 2011). "We hypothesized that Trip10 functions as a tumor suppressor and may be involved in the malignancy of ER-negative (ER-) breast cancer." (PMID 21299869, 2011). "The Trip10 promoter also contains an estrogen receptor (ER)-binding site, which is essential for the gene expression in ER-positive MCF7 breast cancer cells." (PMID 21219604, 2011). "To determine Trip10 methylation in vivo, we examined Trip10 promoter methylation in human breast cancer and liver cancer specimens and adjacent non-tumor tissues." (PMID 21299869, 2011). "The Trip10 promoter was either unmethylated or undermethylated in MSCs and CP70 ovarian cancer cells as revealed by bisulfite sequencing, but the same sequence was moderately methylated in breast cancer cells (MCF7 and MDA-MB-231) and liver cancer cells (HepG2)." (PMID 21299869, 2011).
breast tumor (4 papers, 2011 to 2021). "In ER+ breast tumor cells, DNA methylation of Trip10 was not detectable; however, disrupting ER signalling caused a time-dependent increase in DNA methylation of Trip10 and reduced mRNA levels." (PMID 21299869, 2011). "Trip10 is consistently unmethylated in ER+ breast tumors but hypermethylated in ER- breast tumors." (PMID 21299869, 2011). "Among the cell lines we examined, the DNA methylation level of Trip10 (from highest to lowest) was: brain tumor cells (IMR-32 and U87) > breast tumor cells (MCF7 and MDA-MB-231) > liver cancer cells (HepG2) > ovarian cancer cells (CP70) > MSCs." (PMID 21299869, 2011). "Consistently, the Trip10 promoter is hypermethylated in ER- human breast tumors, but not in ER+ breast tumors." (PMID 21299869, 2011).
lung carcinoma (3 papers, 2015 to 2017). "TRIP10, also named CIP4, was related to lung cancer and chronic lymphocytic leukemia." (PMID 29108269, 2017).
glioma (2 papers, 2013 to 2021). A benign or malignant brain and spinal cord tumor that arises from glial cells (astrocytes, oligodendrocytes, ependymal cells). "We found that the protein level of FLAG-tagged TRIP10 was substantially reduced upon HGF treatment in the U373 glioma cells." (PMID 24023761, 2013). "The top-ranking genes were related to the TRIP10, NR2F6, ACTN4, SBNO2, and TGFB1L1 genes (p < 0.05), and a link between ACTN4 and TGFB1L1 expression and tumorigenesis was shown in glioma samples." (PMID 34722629, 2021).
Huntington disease (2 papers, 2011 to 2021). Huntington disease (HD) is a rare neurodegenerative disorder of the central nervous system characterized by unwanted choreatic movements, behavioral and psychiatric disturbances and dementia. "Trip10 is also a regulator or modulator of cell survival after DNA damage and in the human brain affected by Huntington's disease." (PMID 21299869, 2011). "In human brains, immunoexpression of Trip10 is detected in the nucleus and cytoplasm of neurons, activity and nuclear distribution are higher with more severe Huntington's disease." (PMID 21299869, 2011). "On the other hand, overexpression of Trip10 was observed in human Huntington's disease brain striatum, and neuronal Trip10 immunoreactivity increased with neuropathological severity in the neostriatum of Huntington's disease patients." (PMID 21299869, 2011).
pancreatic cancer (2 papers, 2011 to 2020). "On the other hand, Trip10 directly interacts with WASP family verprolin-homologous protein (WAVE1) in a pancreatic cancer cell line and enhances its phosphorylation by the cytosolic tyrosine kinase c-Abl." (PMID 21299869, 2011). "However, Trip10 overexpression enhances pancreatic cancer cell migration by downregulating the antitumor function of ArgBP2, suggesting that Trip10 contributes to the malignancy of pancreatic cancer." (PMID 21299869, 2011). "ALDOA and PAF1 have recently been described as oncogenes in PDAC, whereas ENO1, RALGDS, TRIP10, and FLNA are known to mediate pancreatic cancer cell proliferation, survival and migration." (PMID 32029502, 2020).
triple-negative breast carcinoma (2 papers, 2015 to 2022). An invasive breast carcinoma which is negative for expression of estrogen receptor (ER), progesterone receptor (PR), and human epidermal growth factor receptor 2 (HER2). "For example, TRIP10 downstream effector of CDC42 is hyperphosphorylated in non-responder cohorts and in triple negative breast cancer, the hypermethylation of TRIP10 is related with the prediction of response to neoadjuvant chemotherapy." (PMID 36393868, 2022).
brain tumor (1 paper, 2011). "Overexpressed Trip10 was associated with endogenous Cdc42 and huntingtin in IMR-32 brain tumor cells and CP70 ovarian cancer cells." (PMID 21299869, 2011).
colorectal cancer (1 paper, 2023). A primary or metastatic malignant neoplasm that affects the colon or rectum. "It had been demonstrated that colorectal cancer enhanced high levels of TRIP10 expression." (PMID 37168510, 2023). "TRIP10, also known as CIP4, is controlled by AKAP9 and aids in the development of colorectal cancer." (PMID 37168510, 2023).
epilepsy (1 paper, 2024). A brain disorder characterized by episodes of abnormally increased neuronal discharge resulting in transient episodes of sensory or motor neurological dysfunction, or psychic dysfunction. "TRIP10 encodes a cytoskeletal binding protein involved in endocytosis that suppresses glucose uptake in response to insulin signaling, GPR108 encodes an orphan G-protein-coupled receptor, and SIK1 encodes a salt-inducible kinase with roles in cancer, epilepsy, and myeloid signaling." (PMID 39302339, 2024).
Infertility (1 paper, 2022). "Unfortunately, Trip10 ablation does not cause infertility in mice so its putative role in fertilization is unclear and could be masked by the redundant function of other genes." (PMID 35721474, 2022).
multiple sclerosis (1 paper, 2024). A progressive autoimmune disorder affecting the central nervous system resulting in demyelination. "The TRIP10 and GPR108 promoters were each captured in contact with a high-confidence variant rs1077667 (PP > 0.99), which is located in an intron of TNFSF14 and is associated with multiple sclerosis." (PMID 39302339, 2024).
cancer (15 papers, 2011 to 2024). A tumor composed of atypical neoplastic, often pleomorphic cells that invade other tissues. "SEPTIN10 is associated with B cell leukemias, while TRIP10 is involved in tumorigenesis and cancer progression." (PMID 36139690, 2022). "We first compared DNA methylation at the Trip10 promoter and first exon in cancer cell lines and somatic stem cells (MSCs) from normal human adults by bisulfite sequencing and qMSP." (PMID 21299869, 2011). "We applied methylation-specific polymerase chain reaction and bisulfite sequencing to determine the DNA methylation of Trip10 in various cancer cell lines and tumor specimens." (PMID 21299869, 2011). "Here we report that Trip10 is differentially methylated in different types of cancer cell lines and tumors." (PMID 21299869, 2011). "In addition, TRIP10 expression has shown to be regulated by DNA methylation in mesenchymal stem cell differentiation and in several types of cancer cell lines and tumors." (PMID 30786922, 2019). "We found that Trip10 is differentially methylated in different cancers." (PMID 21299869, 2011). "Trip10 regulates cancer cell growth and death in a cancer type-specific manner." (PMID 21299869, 2011). "Because Trip10 is differentially methylated in different types of cancer, we speculated that Trip10 functions in cell type-specific manner." (PMID 21299869, 2011). "Trip10 also appears to be involved in tumorigenesis and cancer progression." (PMID 21299869, 2011).
tumor (10 papers, 2011 to 2024). "Trip10 can enhance tumorigenesis or act as tumor suppressor depending on the cell type in which it is expressed." (PMID 21299869, 2011). "Trip10 can be oncogenic or tumor suppressive, increasing IMR-32 cell proliferation and inhibiting CP70 cell proliferation." (PMID 21299869, 2011). "Because PI3K/Akt and MAPK pathways are often aberrantly activated in tumor cells, and they are reported to be associated with Cdc42 and huntingtin, thus we performed qRT-PCR to determine the mRNA expression of Akt and MAPK14 (encoding p38 MAPK) in Trip10-overexpressed CP70 and IMR-32 cells." (PMID 21299869, 2011). "Thus lack of Akt3 expression along with high level of endogenous huntingtin in CP70 cells may be the determinant factors of Trip10-induced tumor suppression." (PMID 21299869, 2011). "Aberrant DNA methylation of Trip10 occurs in vivo and may contribute to neoplasm development." (PMID 21299869, 2011). "To evaluate whether Trip10 function is regulated in a lineage-dependent manner, we used methylation-specific polymerase chain reaction (MSP) and bisulfite sequencing to assess DNA methylation of Trip10 in human primary tumor specimens and cell lines." (PMID 21299869, 2011).
TRIP10 also shares sentences with these, for which no sentence is quoted: nasopharyngeal carcinoma (3 papers); osteosarcoma (3); heart failure (2); lung adenocarcinoma (2); adrenocortical adenomas (1); Alzheimer disease (1); central obesity (1); chronic kidney disease (1); chronic lymphocytic leukemia (1); gout (1); heart disease (1); infection (1); Insulin resistance (1); invasive breast carcinoma (1); invasive ductal carcinomas (1); laryngeal carcinoma (1); liver cancer (1); mammary adenocarcinoma (1); metabolic disease (1); metastatic disease (1); mitochondrial neurogastrointestinal encephalomyopathy (1); muscular dystrophy (1); myocardial infarction (1); ovarian carcinoma (1); psychiatric diseases (1); pulmonary fibrosis (1); renal carcinoma (1); renal cell carcinoma (1); Thrombocytopenia (1).